TG (thyroglobulin)
Description:
Acts as a substrate for the production of iodinated thyroid hormones thyroxine (T4) and triiodothyronine (T3). The synthesis of T3 and T4 involves iodination of selected tyrosine residues of TG/thyroglobulin followed by their oxidative coupling in the thyroid follicle lumen. Following TG re-internalization and lysosomal-mediated proteolysis, T3 and T4 are released from the polypeptide backbone leading to their secretion into the bloodstream. One dimer produces 7 thyroid hormone molecules.
Synonyms: TGN; AITD3
Tractability: Small molecule: it belongs to a druggable protein family. Antibody: UniProt places it where antibodies can reach, with high confidence; UniProt predicts a signal peptide or a membrane-spanning region; its Gene Ontology location is reachable by antibodies, with medium confidence.
Gene: Protein-coding gene on chromosome 8 (132,866,958 to 133,134,903, forward strand). Ensembl gene ENSG00000042832.
Subcellular location: Secreted
Gene Ontology:
Molecular function: identical protein binding; protein binding
Biological process: thyroid gland development; thyroid hormone generation; signal transduction
Cellular component: extracellular region
Genetic constraint (gnomAD): Loss-of-function variants: 263 observed, 326.71 expected, observed/expected ratio (o/e) 0.8, 90% interval 0.73 to 0.89. The upper end of that interval is the gene's LOEUF score, 0.89, which puts it in group 3 of 6, group 1 being the genes least tolerant of losing a copy. Missense variants: 3,557 observed, 3,600.1 expected, observed/expected ratio (o/e) 0.99, 90% interval 0.96 to 1.02. Synonymous variants: 1,389 observed, 1,387.6 expected, observed/expected ratio (o/e) 1, 90% interval 0.96 to 1.05.
Homologues: Orthologues: chimpanzee TG (98% identical), macaque TG (90% identical), dog TG (79% identical), mouse Tg (74% identical), pig TG (74% identical), guinea pig TG (74% identical), tropical clawed frog tg (47% identical), zebrafish tg (42% identical), rat Tg (10% identical), Caenorhabditis elegans ace-1 (5% identical), Drosophila melanogaster Jhe (5% identical), Drosophila melanogaster CG9289 (5% identical), and 19 more. Paralogues in human: NLGN3 (7% identical), NLGN2 (6% identical), NLGN4X (6% identical), CES3 (6% identical), NLGN4Y (6% identical), NLGN1 (6% identical), ACHE (6% identical), CES2 (6% identical), CES1 (6% identical), BCHE (6% identical), CES4A (6% identical), CES5A (6% identical), and 1 more.
Diseases named in the same sentence as TG in open-access papers:
TG is named in the same sentence as 515 diseases in open-access papers, as found by Europe PMC text mining. Sharing a sentence is not in itself a finding about the gene and the disease. The quoted sentences say what the papers report.
hypothyroidism (401 papers, 2005 to 2026). Abnormally low levels of thyroid hormone. "She appeared to have been susceptible to autoimmune conditions, given her history of hypothyroidism with elevated thyroid peroxidase positive antibodies of 49.1 and an thyroglobulin antibody level of 208 (levels below 20 IU/mL are typically considered normal)." (PMID 40126291, 2025). "Severe proteinuria resulted in the loss of immunoglobulins, antithrombotic proteins, and thyroglobulin, with the latter contributing to hypothyroidism." (PMID 40669863, 2025). "Homozygous or compound heterozygous variants in the TPO gene lead to a variable degree of iodine organification deficiency characterized by hypothyroidism with elevated thyroglobulin levels." (PMID 41262259, 2025). "Such pathological processes involve either autoantibodies to thyroid peroxidase (TPO-Ab) and thyroglobulin (Tg-Ab), leading to hypothyroidism, or TSH receptor autoantibodies (TSH-R Ab) causing hyperthyroidism." (PMID 39967901, 2024). "These autoantibodies mainly act on Thyroid peroxidase (TPO) and Thyroglobulin (Tg), resulting in atrophy and destruction of thyroid cells, even causing hypothyroidism." (PMID 39981137, 2024). "Hashimoto’s disease, the most common cause of hypothyroidism, is diagnosed by the presence of anti-thyroid peroxidase and anti-thyroglobulin antibodies." (PMID 38883046, 2024). "Lithium is a classic mood stabilizer for BD and is associated with drug‐induced goiter, hypothyroidism, or rarely hyperthyroidism in some BD cases, by changing the structure of thyroglobulin and inhibiting thyroid hormone release from the thyroid gland." (PMID 37424160, 2023). "Hypothyroidism caused by an inflammatory reaction mediated by T cells specific to thyroglobulin characterizes HT." (PMID 37241088, 2023). "Thyroid autoimmunity (TAI) is commonly characterized by the presence of circulating thyroperoxidase antibodies (TPOAbs) and/or thyroglobulin antibodies (TgAbs) which predisposes to hypothyroidism." (PMID 36714589, 2022). "Thyroid autoimmunity (TAI) is commonly defined as the presence of thyroperoxidase antibodies (TPOAbs) and/or thyroglobulin antibodies (TgAbs), which predisposes an individual to hypothyroidism." (PMID 36714589, 2022). "Based on the blood test data obtained before ICI therapy, hypothyroidism, thyroid-stimulating hormone levels and thyroglobulin antibody levels were associated with the onset of irAEs." (PMID 32664888, 2020). "Sex, N-stage, antithyroid peroxidase antibody (TPO-Ab), antithyroglobulin antibody (TG-Ab), thyroglobulin (TG), and fibrinogen (Fb) were associated with hypothyroidism." (PMID 32461982, 2020). "In addition, HT is the main cause of hypothyroidism, and experimental autoimmune thyroiditis in mice, a common animal model of HT, has been established via injection of LPS and mouse thyroglobulin." (PMID 41170176, 2025). "However, of the hundreds of human thyroglobulin genetic variants, most exhibit increased susceptibility to misfolding with defective export from the endoplasmic reticulum, triggering hypothyroidism as well as thyroidal endoplasmic reticulum stress." (PMID 36362390, 2022). "Patients with HT have hypothyroidism due to thyroid gland damage, which is caused by an excessive inflammatory response against the thyroid gland, mediated by the auto-antibodies anti-thyroglobulin (anti-TG) and anti-thyroid peroxidase (anti-TPO)." (PMID 35366263, 2021). "The presence of antibodies to thyroid peroxidase (TPO-Ab) or thyroglobulin in pregnancy is associated with significant increase in miscarriages, premature deliveries, gestational diabetes, postpartum thyroiditis and permanent hypothyroidism." (PMID 33302910, 2020). "The overt disease is defined by the dramatic loss of thyroid follicular cells (thyrocytes), hypothyroidism, goitre, circulating autoantibodies to two primary thyroid-specific antigens, thyroglobulin (Tg), thyroid peroxidase (TPO), and lowered concentrations of serum TSH and T4." (PMID 15762980, 2005).
hypothyroidism (continued). "Furthermore, group B (< 100 m) was positively associated with autoimmune thyroiditis, thyroid peroxidase and thyroglobulin antibody positivity, and negatively associated with overt hypothyroidism, subclinical hypothyroidism, and goiter compared with the first ladder group(P < 0.05)." (PMID 38167020, 2024). "Thyroglobulin and free thyroxine measurements revealed the presence of hyperthyroidism in 15 (9.6%) and hypothyroidism in 8 (3.2%)." (PMID 40969723, 2025). "S10A8 downregulation affects ATP and Ca2+, not only vascular smooth muscle contraction, but also regulates thyroglobulin (thyroid hormone precursor) synthesis and secretion in thyroid cells, promoting the onset of hypothyroidism." (PMID 40443669, 2025). "A meta-analysis notes that hypothyroidism, the presence of anti-thyroglobulin antibodies, anti-thyroid microsomal antibodies, and anti-thyroid peroxidase antibodies are higher in HCV patients than in controls." (PMID 40868568, 2025). "Blood tests showed hypothyroidism, with normal values of thyroglobulin and anti-thyroglobulin antibodies." (PMID 41146796, 2025). "A possible reason for this condition is the concomitant hypothyroidism indicated by the increases in both the anti-thyroglobulin and thyroid peroxidase antibodies titers with the TSH-receptor antibodies level being in the normal range." (PMID 40729266, 2024). "Serum albumin also acts as a buffer of serum levels of thyroxine before hypothyroidism eventually occurs and once it is lost in urine together with thyroglobulin, the serum concentration of the thyroid hormones also decreases." (PMID 38373933, 2024). "Several studies have found an association between thyroid autoantibodies (thyroyperoxidase or thyroglobulin) and risk of ICI‐induced thyroid dysfunction, and in one study approximately all patients with thyroid autoantibodies developed hypothyroidism." (PMID 38932429, 2024). "We recently reported greater changes in thyroid autoantibody (anti-thyroglobulin and anti-thyroid peroxidase antibodies) titers from baseline to irAE onset in patients with thyrotoxicosis than in those with isolated hypothyroidism." (PMID 39574956, 2024). "Laboratory tests demonstrated a severe hypothyroidism and high-titre serum of antibodies against thyroglobulin." (PMID 38868158, 2024). "A resolution of hypothyroidism and a progressive reduction of the value of antibodies against thyroglobulin occurred." (PMID 38868158, 2024). "Thyroglobulin autoantibodies (TgAA) are a valuable marker to predict the occurrence of hypothyroidism." (PMID 36693083, 2023). "All patients had thyroglobulin levels under 0.2 ng/mL in hypothyroidism condition or <1 ng/mL after rh-TSH stimulation, and AbTg/AbTPO levels were undetectable or under the cut-off." (PMID 37835813, 2023). "At irAE onset, the two patients developing hypothyroidism had normal to undetectable autoantibodies against thyroid peroxidase and thyroglobulin." (PMID 35017151, 2022). "Several patients had a previous history of thrombocytopenia, and three other patients had autoimmune conditions including hypothyroidism, Crohn’s disease, or detectable anti-thyroglobulin antibodies." (PMID 36005648, 2022). "The human disease of hypothyroidism with defective thyroglobulin (either homozygous, or compound heterozygous) can be experimentally modeled in thyrocyte cell culture, or in whole animals, such as mice that are readily amenable to genetic manipulation." (PMID 36362390, 2022). "Hypothyroidism is commonly a disease resulting from similar autoimmune insults as indicated by higher anti-peroxidase and anti-thyroglobulin antibodies." (PMID 34772378, 2021). "Some previous studies have demonstrated that the concentration of thyroid-associated antibodies (i.e., antithyroid peroxidase antibody (TPO-Ab) and antithyroglobulin antibody (TG-Ab)) can be correlated with hypothyroidism." (PMID 32461982, 2020).
hypothyroidism (continued). "In dogs affected with hypothyroidism, autoantibodies have been identified against thyroglobulin, thyroid peroxidase, thyroxine and triiodothyronine, similar to those seen in human lymphocytic thyroiditis." (PMID 26618927, 2015). "Subclinical hypothyroidism is characterised by the presence of autoantibodies against thyroglobulin (TgAA) in serum and elevated serum TSH values with lymphocytic infiltrates in the thyroid gland." (PMID 26401340, 2015). "Elevated levels of anti-thyroperoxidase (anti-TPO) and anti-thyroglobulin (anti-Tg) antibodies frequently accompany hypothyroidism, suggesting an autoimmune basis that may contribute to persistent urticarial symptoms." (PMID 40075855, 2025). "It has been hypothesized that the presence of antithyroid antibodies such as TPO and thyroglobulin antibodies could be a favorable factor leading to hypothyroidism." (PMID 40361497, 2025). "The presence of anti-thyroid peroxidase antibodies or anti-thyroglobulin antibodies is associated with the development of hypothyroidism; however, these test data are not routinely measured in clinical practice." (PMID 40190852, 2025). "In conclusion, KL may interfere with bone tissue, growth hormone receptors, and thyroglobulin, impair hypothyroidism, and function as an endocrine disruptor exposure." (PMID 41012373, 2025). "As one of the most common autoimmune disorders in the world, Hashimoto’s thyroiditis (HT) is characterized by lymphocyte infiltration and thyroid autoantibodies such as against thyroid peroxidase (anti-TPO) or thyroglobulin (anti-TG), which eventually leads to thyroid fibrosis and hypothyroidism." (PMID 38803479, 2024). "Monitoring may include, for example, neck ultrasound every 6 months for 1-2 years and then annually, as well as twice-yearly measurement of thyroid hormones and thyroglobulin, with occasional use of levothyroxine when hypothyroidism is present." (PMID 38427812, 2024). "Furthermore, LPS can trigger thyroid autoimmune inflammation by encouraging TSH-stimulated thyroglobulin and sodium/iodine symporter production, leading to thyroid cell damage and hypothyroidism." (PMID 39185088, 2024). "A 50-year-old woman with myxedema was diagnosed with Hashimoto's disease due to hypothyroidism and the presence of antibodies against thyroid peroxidase (TPOAb) and thyroglobulin (TgAb); she also had thyroid stimulating antibodies (TSAb) without any signs of GD." (PMID 37109715, 2023). "Mechanisms that underlie autoimmune thyroiditis and involve attacking the thyroid gland by autoreactive lymphocytes and autoantibodies against thyroid peroxidase (anti-TPO) and thyroglobulin (anti-TG) lead to impaired production of thyroid hormones and hypothyroidism." (PMID 36431248, 2022). "The increased expression of anti-thyroid peroxidase and anti-thyroglobulin antibodies in patients after radiotherapy suggested that an immune response might be one of the mechanisms of radiation-induced hypothyroidism." (PMID 33391441, 2021). "Extremely preterm infants on TPN were more likely to develop iodine deficiency and had high thyroglobulin levels at around 1 month of age and thus likely to develop hypothyroidism if iodine is not supplemented." (PMID 32492945, 2020). "Indeed, data have shown that patients with elevated thyroglobulin antibodies (TgAbs) and/or thyroid peroxidase antibodies (TPOAbs) at baseline were more likely to develop overt thyroid disease or more severe hypothyroidism following ICI treatment." (PMID 33064663, 2020). "Among vitamin D-deficient cases, an increased serum 25(OH)D ≥ 50 nmol/L was associated with greater reductions in biochemical signs of hypothyroidism and thyroid autoimmune disease including an increase in FT4 and FT3, and large decrease in serum TSH, anti-TPO, anti-TG, and TG." (PMID 29067607, 2017).
hypothyroidism (continued). "Whilst there is no apparent sex predisposition for hypothyroidism or thyroglobulin autoantibody status in dogs, females are more likely to have thyroid hormone autoantibodies than male dogs." (PMID 26618927, 2015). "Our results seem to confirm these findings since the only infant treated with L-thyroxine for hypothyroidism was one of the 6% who never presented anti-TPO and anti-TG antibody positivity during the follow-up, and thus the hypothyroidism must be ascribed to other causes." (PMID 40128881, 2025). "Hypothyroidism may also occur for a variety of reasons, the most common being Hashimoto’s disease, a form of hypothyroidism resulting again from autoimmune damage to the thyroid (in this case, autoantibodies directed against the thyroid antigens thyroid peroxidase and thyroglobulin)." (PMID 36830072, 2023). "However, hypothyroidism from defective thyroglobulin is inherited as an autosomal recessive trait." (PMID 36362390, 2022). "TSHB is the key factor for the clinical diagnosis for hypothyroidism, while TG is the response protein to TSHB that drives the normal physiological behaviors of releasing thyroid hormones." (PMID 39897058, 2025). "Autoantibodies to thyroid peroxidase (TPOAb) and thyroglobulin (TgAb) define preclinical autoimmune thyroid disease (AITD), which can progress to either clinical hypothyroidism or hyperthyroidism." (PMID 38996042, 2025). "Diagnostics confirmed severe hypothyroidism [total thyroxine (TT4) < 0.5 μg/dL, thyroid-stimulating hormone (TSH) 5.54 ng/dL], elevated thyroglobulin autoantibodies (TgAA 131%), hyperglobulinemia, hypoalbuminemia, and mild ionized hypercalcemia." (PMID 41473107, 2025). "The most ordered tests in the diagnosis and treatment of hypothyroidism are thyroid peroxidase antibodies (anti-TPO) and thyroglobulin antibodies." (PMID 39264098, 2024). "A study conducted among Polish women revealed an inverse correlation between TSH, TPOAb, thyroglobulin antibodies (TGAb), and serum VD levels across healthy individuals, AIT patients, and those with hypothyroidism." (PMID 39229277, 2024). "The comparison between the results of cases and controls in the literature for the variables hypothyroidism, positive anti-TPO, positive anti-TG and altered TSH showed a statistically significant difference for hypothyroidism." (PMID 37598033, 2024). "Laboratory results also revealed an increase in both anti-thyroglobulin and thyroid peroxidase antibody titers with concomitant level of TSH-receptor antibodies in the normal range underscoring a condition of hypothyroidism." (PMID 40729266, 2024). "In 22 women with overt hypothyroidism, 14 (63.64%) exhibited a significant elevation of anti-TPO and anti-TG (P = 0.041, P = 0.008), respectively." (PMID 37606882, 2023). "On the contrary, correlations between vitamin D concentrations and antibodies against peroxidase (TPOAb), thyroglobulin (TgAb), and TSH in patients with hypothyroidism seem to exist as well as a positive relationship of vitamin D with T3 levels." (PMID 35399653, 2022). "Complications pertain not only to overt hypothyroidism, but also SCH and the presence of circulating anti-thyroid peroxidase (anti-TPO) and anti-thyroglobulin (anti-TG) antibodies." (PMID 35329880, 2022). "Laboratory tests showed normal pituitary function and confirmed G2 hypothyroidism [TSH 130.0 μIU/ml (0.27–4), ↓ FT4 0.10 ng/dl (0.7–1.48), FT3 2.0 pg/ml (1.71–3.71) ↑ thyroglobulin 187 ng/ml (normal range 3–40)]." (PMID 36713496, 2022). "Thyroglobulin (Tg) is the main serum marker for DTC, especially when measured during hypothyroidism or after stimulation with recombinant thyroid-stimulating hormone." (PMID 35311033, 2022). "Secondary outcome measures: dose of levothyroxine required to treat hypothyroidism, thyroid peroxidase antibodies (anti-TPO), and anti-thyroglobulin antibodies (anti-Tg)." (PMID 30532779, 2018).